TRPC3 (transient receptor potential cation channel subfamily C member 3)
Description:
Forms a receptor-activated non-selective calcium permeant cation channel. [Isoform 2]: Forms a receptor-activated non-selective calcium permeant cation channel. May be operated by a phosphatidylinositol second messenger system activated by receptor tyrosine kinases or G protein-coupled receptors.
Synonyms: TRP3; SCA41
Tractability: Small molecule: a structure with a bound ligand is known; a high-quality ligand is known; it belongs to a druggable protein family. Antibody: UniProt places it where antibodies can reach, with high confidence; its Gene Ontology location is reachable by antibodies, with high confidence; UniProt predicts a signal peptide or a membrane-spanning region. PROTAC: a small molecule that binds it is known.
Target class: Voltage-gated ion channel; Ion channel; Transient receptor potential channel
Gene: Protein-coding gene on chromosome 4 (121,874,481 to 121,952,060, reverse strand). Ensembl gene ENSG00000138741.
Subcellular location: Cell membrane
Pathways (Reactome):
Hemostasis: Effects of PIP2 hydrolysis; Elevation of cytosolic Ca2+ levels
Developmental Biology: Role of second messengers in netrin-1 signaling
Transport of small molecules: TRP channels
Gene Ontology:
Molecular function: calcium channel activity; inositol 1,4,5 trisphosphate binding; protein binding; store-operated calcium channel activity; calcium-activated cation channel activity
Biological process: calcium ion transmembrane transport; positive regulation of calcium ion transport into cytosol; positive regulation of cardiac muscle hypertrophy in response to stress; response to ATP; response to calcium ion; calcium ion transport; phototransduction; regulation of cytosolic calcium ion concentration; single fertilization
Cellular component: plasma membrane; cation channel complex; membrane
Genetic constraint (gnomAD): Loss-of-function variants: 49 observed, 82.79 expected, observed/expected ratio (o/e) 0.59, 90% interval 0.47 to 0.75. The upper end of that interval is the gene's LOEUF score, 0.75, which puts it in group 3 of 6, group 1 being the genes least tolerant of losing a copy. Missense variants: 850 observed, 1,137 expected, observed/expected ratio (o/e) 0.75, 90% interval 0.71 to 0.79. Synonymous variants: 398 observed, 427.07 expected, observed/expected ratio (o/e) 0.93, 90% interval 0.86 to 1.01.
Homologues: Orthologues: chimpanzee TRPC3 (99% identical), macaque TRPC3 (99% identical), pig TRPC3 (98% identical), dog TRPC3 (98% identical), rabbit TRPC3 (98% identical), mouse Trpc3 (93% identical), rat Trpc3 (93% identical), guinea pig TRPC3 (90% identical), tropical clawed frog trpc3 (88% identical), zebrafish trpc3 (74% identical), Caenorhabditis elegans trp-1 (34% identical). Paralogues in human: TRPC7 (74% identical), TRPC6 (69% identical), TRPC5 (35% identical), TRPC4 (34% identical), TRPC1 (29% identical).
Diseases named in the same sentence as TRPC3 in open-access papers:
TRPC3 is named in the same sentence as 148 diseases in open-access papers, as found by Europe PMC text mining. Sharing a sentence is not in itself a finding about the gene and the disease. The quoted sentences say what the papers report.
cardiac hypertrophy (34 papers, 2007 to 2025). "TRPC3 interaction with other membrane-bound proteins has been reported to be associated with muscular dystrophy, myocardial hypertrophy, and atrophy; each was activated with different upstream stimuli." (PMID 36903347, 2023). "High-salt diet has been demonstrated to augment cardiac mitochondrial TRPC3 expression, leading to ROS production, mitochondrial dysfunction and cardiac hypertrophy, whereas TRPC3 deficiency inhibited cardiac hypertrophy and improved mitochondrial function." (PMID 36012897, 2022). "TRPC3 has also been implicated in cardiac hypertrophy, and gene deletion of Trpc3 and Trpc6 in mice protected against pressure-induced cardiac remodeling." (PMID 33868385, 2021). "These gain- and loss-of-function studies of TRPC3/C6 channels prove that they are critical components of cardiac remodeling induced by Gq-coupled receptor-induced cardiac hypertrophy." (PMID 32079284, 2020). "For example, a series of gene knock-out studies found that TRPC1, TRPC3, and TRPC6 are associated with cardiac hypertrophy and that deletion of or impaired function of TRPC3 leads to cardiac conduction block." (PMID 32158769, 2020). "Mechanical stress causes cardiac hypertrophy and fibrosis; TRPC3 or Nox2 knockout only affect cardiac fibrosis." (PMID 32079284, 2020). "TRPC3 has been implicated in many cardiovascular diseases, such as myocardial hypertrophy, heart failure, myocardial infarction, and AF." (PMID 31871548, 2019). "This suggests that multiple receptors are linked to a common enzymatic pathway that leads to the activation of TrpC3 and to transcription of genes associated with cardiac hypertrophy." (PMID 17726532, 2007). "TRPC3 deficiency attenuates cardiac hypertrophy by alleviating cardiac mitochondrial dysfunction." (PMID 37253771, 2023). "The role of Ca2+/NFAT signaling in cardiac hypertrophy is well established, and local Ca2+ influx through TRPC3/6 channels may be a putative mechanism underlying activation of calcineurin-NFAT signaling pathway in rodent myocardium." (PMID 29872396, 2018). "We therefore examined whether TrpC3 is necessary for the increase in cell size associated with cardiac hypertrophy." (PMID 17726532, 2007). "In vivo, Pyr3 reduces cardiac hypertrophy and transition to heart failure in mice subjected to pressure overload, whereas Pyr10-mediated TRPC3 inhibition alleviates systemic inflammatory responses in mice after treatment with lipopolysaccharide." (PMID 41118703, 2025). "It is noteworthy that specific inhibition of TRPC3 prevented Ca2+-dependent activation of NFAT, which precedes cardiac hypertrophy and fibrosis, suggesting TRPC3 channels as novel drug targets to prevent cardiac fibrosis in the human heart." (PMID 39595542, 2024). "Our study suggests that the regulation of cardiac hypertrophy by TRPC3 plays an important role in this conversion process." (PMID 37511045, 2023). "TRPC3 predominantly influences pressure overload cardiac remodelling and cardiac fibrosis instead of cardiac hypertrophy by activating Nox2-derived ROS signalling in cardiomyocytes and fibroblasts." (PMID 36903347, 2023). "Previous studies using the same Trpc3−/− mice have reported TRPC3 as an important factor in cardiac hypertrophy, particularly in the LV." (PMID 37511045, 2023). "On the other hand, the specific TRPC3 inhibitor, Pyr3, attenuates the adaptive hypertrophy induced by pressure overload in mice, once again supporting the significant role of TRPC3 in cardiac hypertrophy." (PMID 36291148, 2022). "TRPC3 ablation antagonized cardiac hypertrophy induced by high salt intake, which was achieved by restoring the synthesis of ATP and the activity of complex I and II enzyme in mitochondria." (PMID 35118147, 2021). "Transient receptor potential channel, canonical 3(TRPC3), residing in mitochondria, also exerted regulatory roles in high salt-induced cardiac hypertrophy by mediating mitochondrial function." (PMID 35118147, 2021).
cardiac hypertrophy (continued). "The importance of TRPC3 channels in cardiac hypertrophy was first demonstrated by the Molkentin group, who observed cardiac hypertrophy in cardiomyocyte-specific transgenic mice overexpressing TRPC3." (PMID 32079284, 2020). "Downregulation of FKBP52, which has been revealed as a critical interaction molecule for TRPC3, promotes TRPC3-mediated cardiac hypertrophy." (PMID 32079284, 2020). "Conversely, the overexpression of TRPC3 in transgenic mice increased cardiac hypertrophy through calcineurin/NFAT activation when mice were subjected to angiotensin-II and phenylephrine treatment or pressure overload." (PMID 30881310, 2019). "TRPC3 is highly expressed in the heart and participates in the pathogenesis of cardiac hypertrophy and heart failure as a pathological response to chronic mechanical stress." (PMID 31772600, 2019). "Inhibition of TRPC3/6 channels have been reported to attenuate heart failure through suppressing myocardial hypertrophy and interstitial fibrosis." (PMID 29872396, 2018). "Neurohumoral factor-induced cardiac hypertrophy was also mediated by the increase of TRPC3/C6 expression." (PMID 28936433, 2017). "By contrast, reduction of cGMP/PKG signaling by guanylate cyclase-A gene deletion is reported to develop spontaneous cardiac hypertrophy through TRPC3/6 channel activation." (PMID 28936433, 2017). "A recent study has shown that activation of TRPC3 and 6 channels participates in the generation of cardiac hypertrophy." (PMID 23285142, 2012). "Our finding that TrpC3 is involved in regulating cardiac hypertrophy agrees with three recent studies that appeared during the preparation of this manuscript." (PMID 17726532, 2007). "First, we identified TrpC3 from an unbiased screen for ion channel genes that regulate cardiac hypertrophy, providing independent confirmation that TrpC3 mediates hypertrophy." (PMID 17726532, 2007). "Importantly, atypical trafficking of TRPC3 channels can lead to diseases, including cardiac hypertrophy, hypertension, and Alzheimer’s disease." (PMID 39108834, 2024). "Inhibition of TRPC3 has been explored as a possible intervention for cardiac hypertrophy in a mouse model, where some improvement was seen, but effects were limited by lack of TRPC3 inhibitor compounds with a desirable ADME (absorption, distribution, metabolism and excretion) profile." (PMID 37759438, 2023). "Additionally, TRPC3 plays a significant role in cardiac hypertrophy, implicating cardiac function and pathology through the calcineurin–nuclear factor of an activated T-cell (NFAT) signaling pathway." (PMID 37511045, 2023). "In addition, infusion of neurohumoral factor also increased TRPC3/C6 expression and induced cardiac hypertrophy." (PMID 32079284, 2020). "The TRPC3 KO mice also showed potential protection from pathologic cardiac hypertrophy." (PMID 32872338, 2020). "This property seems to change in diseased conditions, where aberrant TRPC3 expression or function can contribute to the pathophysiology of ataxia, cardiac arrhythmias, cardiac hypertrophy, cardiac and renal fibrosis, to allergic airway disease, or to inflammatory hyperalgesia." (PMID 31947602, 2020). "In contrast, AngII-induced cardiac hypertrophy is attenuated by the suppression of TRPC3 and Nox2." (PMID 32079284, 2020). "This original study clearly indicated increased TRPC3 expression in cardiomyocytes without any specific stimuli causes cardiac hypertrophy." (PMID 32079284, 2020). "TRPC3 and 6 have been shown to be involved in the development of cardiac hypertrophy in rat, mouse, and human cardiomyocytes but may also contribute to Ca entry, which is in accordance with our results." (PMID 31498847, 2019). "This prominent study clearly indicated that TRPC3 expression per se evokes cardiac hypertrophy." (PMID 28936433, 2017). "TRPC3 expression is up-regulated in multiple rodent pathological cardiac hypertrophy models." (PMID 22802050, 2012).
cardiac hypertrophy (continued). "Our screens identified TrpC3 as a mediator of cardiac hypertrophy." (PMID 17726532, 2007). "In addition, recent evidence showed that several transient receptor potential channels (TRP), including TRPV1 and TRPC3, are involved in high-salt intake–induced cardiac hypertrophy by mediating mitochondrial function via regulating mitochondrial calcium uptake." (PMID 33996809, 2021). "Interestingly, cardiac fibrosis was diminished in TRPC3-deficient mice in response to mechanical stresses without any effect on cardiac hypertrophy." (PMID 32079284, 2020). "In addition, AngII-induced cardiac hypertrophy is mediated by both TRPC3 and TRPC6." (PMID 32079284, 2020). "Consistent with the results of studies investigating ectopic expression models of TRPC3/C6, cardiomyocyte-specific overexpression of a dominant-negative TRPC3/C6 mutants suppressed both neurohumoral-factor-induced and pressure-overload-induced cardiac hypertrophy and dysfunction." (PMID 32079284, 2020). "Thus TrpC3 may represent an important therapeutic target for the treatment of cardiac hypertrophy and heart failure." (PMID 17726532, 2007). "Several mouse models of heart disease suggest an important role for TRPC3 and TRPC6 channels in the development of cardiac hypertrophy." (PMID 41118703, 2025). "This creates a positive feedback loop, where increases in the TRPC3 and TRPC6 expression further amplify the CaN-NFAT pathway and contribute to cardiac hypertrophy." (PMID 40498020, 2025). "The overactivation of TRPC3 and TRPC6 channels, coupled with the CaN-NFAT signaling pathway, plays a crucial role in the development of myocardial hypertrophy by enhancing the Ca2+ influx and promoting pathological cardiac remodeling." (PMID 40498020, 2025). "There is evidence that other canonical subunits are involved in cardiac hypertrophy, most notably Ca2+ influx through TRPC1, TRPC3, and TRPC6 channels initiates the calcineurin-NFAT hypertrophy signalling pathway." (PMID 38672459, 2024). "This study clearly indicated that TRPC3/C6 activates the CaN/NFAT pathway and induces pathological cardiac hypertrophy." (PMID 32079284, 2020). "Nicotine-induced cardiac hypertrophy, which includes NFAT activation, is also suppressed by TRPC3 downregulation." (PMID 32079284, 2020). "Using animal models of pressure overload-induced heart hypertrophy, different studies demonstrated that TRPC1, TRPC3, and TRPC6 are upregulated in heart." (PMID 30881310, 2019). "Taken together these results indicate that TrpC3 plays an important role in the induction of both ANP and BNP, the two best-studied cardiac hypertrophy genes." (PMID 17726532, 2007). "The experiments above suggest that TrpC3 expression is necessary for the expression of both ANP and BNP, two genes that play an important role in cardiac hypertrophy." (PMID 17726532, 2007). "TRPC3 is a non-selective cation permeable channel that performs a critical role in several physiological activities, including cardiac hypertrophy, vascular smooth muscle contraction, and insulin secretion among others." (PMID 39108834, 2024). "Additionally, previous studies have consistently shown the essential role of GPCR-stimulated Ca2+ signalling through DAG-activated TRPC3 and TRPC6 in myocardial hypertrophy and interstitial fibrosis." (PMID 36903347, 2023). "Kass’s group reported that TRPC3/C6 double-knockout mice, but not those with single knockout of either channel, became resistant to pressure-overload-induced cardiac hypertrophy." (PMID 32079284, 2020). "Increased expression of TRPC3 and TRPC5 channels in the hypertrophied and failed hearts indicates that the TRPC channels may contribute to myocardial hypertrophy pathogenesis through calcium signaling and calcineurin/NFAT path activation." (PMID 32641948, 2019).
cardiac hypertrophy (continued). "Studies have consistently shown that particularly DAG-activated TRPC3 and TRPC6 (TRPC3/6) channels function as an important mediator of GPCR-stimulated Ca2+ signaling pathway that may participate in pathological cardiac hypertrophy." (PMID 29872396, 2018). "Considering the role of TRPC3/6 heterotetramer channels in cardiac hypertrophy, TRPC6 protein signaling complex, including TRPC1 and TRPC3, may function as mechano-activated cation channels in the cardiovascular system." (PMID 28936433, 2017). "Other researchers also convincingly demonstrated an involvement of TRPC3 and TRPC6 and transgenic mice expressing dominant-negative forms of TRPC3, TRPC6 and TRPC4, which will also inhibit TRPC1 heteromeric, but not homomeric, channels are almost completely protected from cardiac hypertrophy." (PMID 25268281, 2014). "Interestingly, while cardiac hypertrophy was not affected by TRPC3 deletion, cardiac fibrosis was diminished in TRPC3-deficient mice in response to pressure overload." (PMID 28936433, 2017).
Ataxia (27 papers, 2014 to 2026). Ataxia refers to impaired coordination of voluntary muscle movement. "TRPC3 is essential for metabotropic type 1 glutamate (mGluR1) receptor signaling in Purkinje cells, and dysfunction of TRPC3 channels causes ataxia." (PMID 38892448, 2024). "Gain-of-function point mutations in TRPC3 have been shown to cause spinocerebellar ataxia (SCA), both in a patient with SCA41 and the Moonwalker (Mwk) mouse mutant." (PMID 37759438, 2023). "A study on moonwalker mice has revealed that mutation in TRPC3 protein leads to abnormal channel opening and passage of Purkinje cells and cerebellar ataxia." (PMID 37332910, 2023). "Observations link the pathological mechanisms underlying several different genetic forms of cerebellar ataxia to TRPC3-orchestrated dysfunction in Ca2+ signaling." (PMID 35265671, 2022). "Mwk mouse is a spontaneous mutant mouse that shows abnormal Purkinje cell development and cerebellar ataxia due to increased calcium influx to Purkinje cells through mutated TRPC3 channels, and TRPC3 was also identified as the gene causing SCA41." (PMID 34536317, 2021). "Loss of control in TRPC3’s activity hampered the growth and differentiation of Purkinje cells and finally led to ataxia." (PMID 31936014, 2020). "The Moonwalker (Mwk) mouse is a model of dominantly inherited cerebellar ataxia caused by a gain-of-function mutation in the transient receptor potential (TRP) channel TRPC3." (PMID 25908616, 2015). "Both genetic loss of Trpc3 and the dominant Moonwalker (Mwk) gain-of-function point mutation in Trpc3 result in cerebellar ataxia in the mouse, highlighting the importance of Purkinje cell calcium homeostasis for proper cerebellar function." (PMID 25908616, 2015). "Recently, we have identified the first functionally pathogenic variant (R672H) in the human TRPC3 gene in a patient with adult-onset cerebellar ataxia." (PMID 25908616, 2015). "The fact that both loss and gain of TRPC3 function lead to cerebellar ataxia has been previously attributed as “conflicting”." (PMID 24797279, 2014). "Similar to the Mwk mouse phenotype, knockout mice deficient in the genes encoding mGluR1, Gαq, IP3R1, TRPC3, and PKCγ all exhibit cerebellar ataxia." (PMID 24797279, 2014). "Supporting this, a methylation-regulating TRPC3 promoter polymorphism was found to be enriched in patients with idiopathic cerebellar ataxia." (PMID 24797279, 2014). "Similarly, overactivated TRPC3 channel activities in Purkinje neurons, as shown by the gain-of-function mutation (T635A) in the Trpc3 gene, account for the impaired dendritic development and survival underlying cerebellar ataxia." (PMID 40498020, 2025). "SCA44 is a spinocerebellar ataxia arising from mutations in mGluR1 receptors, which in turn may lead to aberrant Ca2+ signalling through TRPC3." (PMID 37759438, 2023). "Patients with a point mutation of TRPC3 gene (R762H) show late-onset unidentified ataxia." (PMID 30060610, 2018). "Furthermore, GOF mutation in TRPC3 in the S4–S5 linker of the channel leads to ataxia (moonwalker mouse)." (PMID 29736621, 2018). "For example, the moonwalker mouse model carries a mutation leading to constitutive activation of TRPC3 channels and a dominantly inherited cerebellar ataxia; perhaps relatedly, mutated forms of PKCγ found in SCA14 fail to phosphorylate TRP channels resulting in sustained Ca2+ entry into PNs." (PMID 28518055, 2017). "Moreover, TRPC3 signaling has been linked to several other genetic forms of cerebellar ataxia in human and mouse including SCA1, SCA14, SCA15 and mutations in the GluD2 receptor." (PMID 25908616, 2015). "The increasing use of next-generation sequencing approaches for the genetic diagnosis of cerebellar ataxia is poised to fully elucidate the role that TRPC3 mutations may play in human cerebellar ataxia." (PMID 24797279, 2014). "Furthermore, the mutant variant R672H of the human TRPC3 gene leads to cerebellar ataxia." (PMID 33240883, 2020).